ADH1C (alcohol dehydrogenase 1C (class I), gamma polypeptide)
Diseases named in the same sentence as ADH1C in open-access papers (continued):
Sharing a sentence is not in itself a finding about the gene and the disease.
tumor (19 papers, 2017 to 2025). "Intriguingly, ADH1C stands out as a well-validated tumor suppressor, and its loss in high-risk patients likely contributes to metabolic rewiring and loss of growth control." (PMID 41169384, 2025). "In the analysis of the variables associated with the OS, age, TNM stage, N stage, tumor length, and ADH1C were significantly associated with OS." (PMID 36212135, 2022). "In addition, independent associations between TNM stage, tumor length, and ADH1C and DFS were confirmed by multivariate analysis." (PMID 36212135, 2022). "In addition, in multivariate analysis, age, TNM stage, tumor length, and ADH1C were independently associated with OS." (PMID 36212135, 2022). "The analysis results showed that the expression levels of G6PD, KIF20A, NDRG1, RECQL4, and MCM4 were significantly higher in HCC tumor tissues than in normal tissues, while ADH1C was significantly downregulated in HCC tumor tissues." (PMID 41169384, 2025). "All-trans-retinol dehydrogenase NAD+ (ADH1B), ADH1C, and CA-II showed the lowest levels in both S and D tumor samples." (PMID 39195201, 2024). "The non-tumor tissue was well classified by Galphai2, CA-II, ADH1C, CEH, and IgGFc-binding protein, while ADH1B contributed with a lower MDA score." (PMID 39195201, 2024). "EREG demonstrated higher RNA expression in NSCLC than in normal lung epithelial cells, while there was little difference in ADH1C between normal and tumor lung cells, which needs additional experiments for validation." (PMID 37077811, 2023). "Using bioinformatics, we screened six genes for their potential to influence tumor lipid metabolism (ADH1C, APEX1, ME1, S100A10, ACACA, and CYP2C9), and a prognosis model for HCC patients was constructed." (PMID 36456877, 2022). "CA-II, ADH1C, CEH, IgGFc-binding protein, and ADH1B were all found to be less-abundant proteins in both regions of the tumor analyzed, suggesting their possible down-expression in CRC cells." (PMID 39195201, 2024). "Based on the MDA scores of the single groups, Galphai2, CA-II, ADH1C, CEH, and IgGFc-binding protein, showing the highest MDA score in the H sample group, appeared to classify the non-tumor control tissue well." (PMID 39195201, 2024). "The SNPs of ADH1B rs1229984, ADH1C rs1789924, and ALDH2 rs671 were detected by Sanger sequencing using formalin-fixed paraffin-embedded tumor samples." (PMID 36212135, 2022). "Consistent with the results from the datasets, the expression levels of ADH1C, SLC26A2, and NANS were substantially decreased in tumor tissues compared with those in the corresponding adjacent tissues (P<0.01)." (PMID 36110947, 2022). "Our results showed that the expression level of ADHs including ADH1A, ADH1B, ADH1C, and ADH6 was obviously decreased with the progression of tumor malignancy." (PMID 33287761, 2020). "In addition, ADH1C was identified in a study to be a key gene in tumor microenvironments in HCC, and in consideration of its role as an important regulator of intestinal inflammation, the effect of ADH1C in immunity deserves further consideration." (PMID 36671526, 2023). "It is possible that the product of the ALDH3B2 gene could serve as the enzyme protecting tumor colon cells from ROS (reactive oxygen species), considering that expression of other alcohol dehydrogenase isozymes (ADH1B and ADH1C) is decreased." (PMID 30967137, 2019). "The expression of ADH1C, SLC26A2, and NANS was determined in the TCGA-COADREAD dataset (n=689) and four large external cohorts (GSE106582, n=194; GSE31737, n=80; GSE117606, n=208; GSE74602, n=60), and the expression of the three genes were compared between tumor and control tissues." (PMID 36110947, 2022). "Most of these genes, including ADH1B, ALDH1A1, ADH1C and ALDH2, were significantly down-expressed in ER+ or ER- tumors compared to tumor-adjacent normal tissues, although none showed significant differential expression by alcohol intake in either tissue type." (PMID 28899409, 2017).
infection (1 paper, 2011). The state of being infected such as from the introduction of a foreign agent such as serum, vaccine, antigenic substance or organism. "qPCR analysis demonstrated that for genes that were affected either by infection challenge (e.g. AGR2, G6PC, RETNLB) or diet (e.g. IL1R2, CD3G, ADH1C), gene expression levels of the microarray were verified." (PMID 21698235, 2011).
ADH1C also shares sentences with these, for which no sentence is quoted: alcoholism (8 papers); Parkinson disease (3); alcohol cirrhosis (2); Obesity (2); oesophageal cancer (2); acute coronary syndrome (1); adenocarcinoma (1); atherosclerosis (1); bladder cancer (1); breast tumors (1); cardiovascular disease (1); cervical cancer (1); cleft lip (1); cleft palate (1); dementia (1); duodenal cancer (1); Hypertension (1); hypopharynx cancer (1); ischemia (1); liver cirrhosis (1); lymphoma (1); muscular disease (1); myeloma (1); neurodegenerative disease (1); non-alcoholic steatohepatitis (1); opioid use disorder (1); oral cavity cancer (1); oral squamous cell carcinoma (1); psoriasis (1); sarcoma (1).
A further 1 disease shares a sentence with ADH1C in 1 paper.